BCL2 (BCL2 apoptosis regulator)
Diseases named in the same sentence as BCL2 in open-access papers (continued):
Sharing a sentence is not in itself a finding about the gene and the disease.
cancer (continued). "Bcl-2 proteins mediate a number of processes including development, homeostasis, autophagy, and innate and adaptive immune responses and their dysregulation underpins a host of diseases including cancer." (PMID 31940915, 2020). "In addition, the level of Bcl‐2 in cancer tissues of patients with low AFP serum was lower than that of patients with high serum AFP." (PMID 33090723, 2020). "In addition, an increased level of BAX vs decreased level of Bcl-2 pushed cancer cells into apoptosis." (PMID 32952942, 2020). "Also, of note, miRNA-21, a circulating tumor biomarker for early cancer diagnosis, is capable of mediating the expression of Bcl-2 and PI3K/AKT/mTOR signaling pathway." (PMID 32076440, 2020). "Bcl-2 overexpression is observed in the majority of human cancers." (PMID 32650545, 2020). "BCL-2 is a known cancer target with several potential inhibitors under validation." (PMID 32884211, 2020). "Cancer cells harness the calcium machinery of the host cell to proliferate at a maximum level and reduced apoptotic response by relying upon the high level of Bcl-2." (PMID 33383780, 2020). "Thus, it seems that as a complementary anti-cancer drug, silibinin can overcome chemoresistance in cancer therapy through downregulation of miRNAs such miR-155 and Bcl-2." (PMID 32489562, 2020). "Similarly, flow cytometry results showed that apoptosis in cancer cells increased with the decrease in Bcl2 expression." (PMID 33135339, 2020). "Due to the recognized relevance of this family in cancer progression and response to therapy, different efforts have made in recent years in order to develop small molecules able to target anti-apoptotic proteins such as Bcl-2, Bcl-xL and Mcl-1." (PMID 32455818, 2020). "Caffeic acid, a component detected in high concentrations in our extract, has also been studied for its apoptotic effect on cancer cells: it induced apoptosis in human cervical cells via the mitochondrial pathway, which included a downregulation of Bcl2 and a release of cytochrome c." (PMID 32872275, 2020). "Other studies have also reported that bcl2 was overexpressed in poorly differentiated carcinomas." (PMID 32104177, 2020). "The altered role of the Bcl-2 has been reported in many carcinomas." (PMID 33383780, 2020). "In this manuscript, we thus explored whether BCL-2 inhibition would bypass the protective effects of CAFs, how CAFs might mitigate BCL-2 dependency otherwise and whether additional vulnerabilities might ensue from the CAFs/luminal cancer cell interactions." (PMID 30631150, 2019). "Overexpression of Bcl-2 and other antiapoptotic proteins is common in many cancers." (PMID 31032366, 2019). "Bcl-2 protein determines the response of cancer cells to chemotherapeutic agents." (PMID 31143550, 2019). "As there are a multitude of ways that cancer cells can alter Bcl-2 protein function, testing a limited set of expressed biomarkers may not predict patient response." (PMID 31681471, 2019). "Indeed, these compounds trigger a down-regulation of the expression of anti-apoptotic proteins (e.g., Bcl-2) and an up-regulation of that of pro-apoptotic proteins (e.g., Bax) in cancer cells, as shown by the biological assays." (PMID 31671922, 2019). "It was previously demonstrated that P. pentosaceus could increase Bax/Bcl-2 ratio which subsequently increases mitochondria-mediated membrane permeability and inhibits cancer cells." (PMID 30972037, 2019). "Further experiments could be performed to recognize the differences in the results for different isoforms of BCL2 and may be useful for the treatment of cancers." (PMID 31842912, 2019). "However, follow up studies, with correlation between Bcl-2 expression and cancer specific 5-year survival statistics, need to be done for definite assessment of the prognostic value of Bcl-2 in CRC." (PMID 31754362, 2019). "As Bcl-2 is often over expressed in cancers, we next studied The Cancer Genome Atlas (TCGA) to see if Bcl-2 and PRDM10 expression may be correlated." (PMID 31143550, 2019).
cancer (continued). "This may be due to the promotion of cancer cell apoptosis via regulation of Bax and Bcl-2 expression." (PMID 30578377, 2019). "Therefore, the metabolic state has important implications for therapy as cancer cells can indirectly become resistant to chemotherapy by rewiring/reprogramming metabolism and, thus, changing their BCL-2 protein landscape." (PMID 31405035, 2019). "In addition to apoptosis inhibition, the Bcl2 protein is correlated with cancer resistance to chemotherapeutic drugs." (PMID 31205469, 2019). "In HCT-15 cells, reduced transcription of cell cycle mediating genes (CCND1, PCNA, CDK2, CDKN1B), and reduced transcription of anti-apoptotic genes (BMI1, BIRC5 and BCL2), support a cancer suppressive and favorable FOXO3/FOXM1 ratio upon combined TNKSi/MEKi treatment." (PMID 30717152, 2019). "Incubation of the cancer cells in the presence of 1.5 mg mL−1 MtRV extract for 24 h simultaneously increased the expression of the Bax proapoptotic gene and decreased that of the antiapoptotic Bcl-2 gene." (PMID 30610508, 2019). "Several studies have shown the role of BCL-2 in cancer cell survival and drug resistance." (PMID 31288832, 2019). "Several results from cancer studies have been shown that GAPLNC can modulate the expression of Bcl‐2 by down‐regulating miR‐211.14, 21 Here, we tested this hypothesis by either silencing or overexpressing GAPLINC in HUEVC cells." (PMID 31589383, 2019). "Moreover, abnormal expressions of Bcl-2 are commonly found in cancer cells, which increase the chemoresistance of these cells." (PMID 31581581, 2019). "Many cancer cells depend on anti‐apoptotic B‐cell lymphoma 2 (Bcl‐2) proteins for their survival." (PMID 30266036, 2019). "Finally, as BCL2 proteins are all highly overexpressed in cancers, they represent prime candidates as antigens for anti-cancer therapy." (PMID 31569576, 2019). "It is reported that combination with venetoclax could enhance the anti-cancer effect of tamoxifen in patients with ER and BCL2-positive metastatic breast cancer and a clinical study is undergoing." (PMID 30961650, 2019). "Thus, targeting cancer cells for apoptosis via disrupting Bcl-2 protein interactions is complicated as our current knowledge of these single-cell dynamics is limited." (PMID 31681471, 2019). "Venetoclax, a drug targeting Bcl-2, is currently approved for the treatment of a refractory form of chronic lymphocytic leukemia, and other drugs that directly target Bcl-2-family proteins are now in cancer clinical trials." (PMID 31181072, 2019). "Interestingly, the anti-apoptotic protein Bcl-2 expression level seems to be a determinant for cancer cell sensitivity to cisplatin." (PMID 30884858, 2019). "Previous studies have indicated that increase in pro-apoptotic proteins Bax and Bak with decreased levels of anti-apoptotic proteins like Bcl-2 in both total and mitochondrial fractions are a major driving force in mitochondrial dysfunction and subsequent apoptosis in some anti-cancer treatments." (PMID 31011292, 2019). "Thus, targeting the anti-apoptotic Bcl-2 proteins represents a promising strategy for the treatment of cancer." (PMID 31143550, 2019). "Although BCL-2 proteins may exert multiple cellular functions, e.g. in regulating mitochondrial physiology and nuclear processes (reviewed in3), the main function of the antiapoptotic BCL-2 proteins in cancer cells is to prevent mitochondrial apoptosis." (PMID 31801941, 2019). "Bcl-2 protein is estimated to be overexpressed in almost as many as half of all human cancers." (PMID 30781512, 2019). "Bcl2 is an upstream effector molecule in the apoptotic pathway and has been recognized as a potent inhibitor of apoptosis and shown to be overexpressed in various types of cancer including PanCa." (PMID 30674344, 2019).
cancer (continued). "Moreover, silencing of Akt1 and 2 isoforms was found to decrease the expression of proteins regulating cancer cell survival and proliferation such as cyclooxygenase-2, B-cell lymphoma 2 (Bcl-2), cyclin D1, and survivin." (PMID 31252679, 2019). "Since Bcl-2 expression plays a major role in survival of various cancers, we investigated whether 4,5-diCQA affected the Bcl-2 expression in the DU-145 cells." (PMID 31263600, 2019). "ABT-737, a B cell lymphoma-2 (Bcl-2) family inhibitor, activates apoptosis in cancer cells." (PMID 31906234, 2019). "Second, we also determined whether the ABT‐199 concentration (1 μM) and duration of the treatment (2 h) used in the PAC experiments could kill effectively Bcl‐2‐dependent cancer cells known to be sensitive to ABT‐199." (PMID 30266036, 2019). "Indeed, the design of Venetoclax based on BCL2 knowledge is the best evidence that a treatment targeting apoptotic proteins can get us closer to curing cancer." (PMID 31569576, 2019). "Therefore, the myriad of variations in expression and function of pro- and anti-apoptotic Bcl-2 proteins combine in a cancer cell to determine how that cell responds to a drug designed to activate that process." (PMID 31681471, 2019). "A better understanding of gene expression, mutational profile, and molecular mechanisms of pro-survival Bcl-2 proteins in different cancer types, could help to clarify their role in cancer development and may guide advancement in drug discovery." (PMID 31825969, 2019). "This has also been demonstrated in cancer cells, treatment of prostate cancer cell DU145 and PC3 caused decreased growth and increased apoptosis with decreased anti-apoptotic protein Bcl-xl and Bcl-2 and increased pro-apoptotic protein Bax and Bak." (PMID 31067776, 2019). "However, the main mechanism of this inhibitor is binding to Mcl-1 as a supplemental therapy in Bcl-xLlow or Bcl-xL− cancer cells or cells with resistance to Bcl-2 inhibitors." (PMID 31662966, 2019). "A major mechanism contributing to cancer drug resistance is the avoidance of drug-induced apoptosis, which has been shown to be attributed to the overexpression of various anti-apoptotic proteins such as BCL2." (PMID 35582270, 2019). "The shifting balance of priming during development is also influenced by changes in pro-apoptotic Bcl-2 proteins, although in relation to cancer predisposition, individual BH3-only proteins seem not to have significant roles in the development of most tissues." (PMID 31681471, 2019). "Among the 76 basal-like triple-negative FMCs, 18% (14/76) were Bcl-2–positive, and were associated with a better outcome in terms of overall survival, and specific survival, independently of the pathologic nodal stage or the WHO cancer stage." (PMID 30630524, 2019). "Bcl-2 over-expression has been observed in a wide variety of cancer." (PMID 31143550, 2019). "Some target genes of miR-204 have been validated in cancer cells, such as BCL2 in cholangiocarcinoma, colon cancer and neuroblastoma, BNDF and JAK 2 in breast cancer, Cyclin D2 in retinoblastoma, EPHB2 in glioma, IGFPB5 in papillary thyroid carcinoma, and SHP2 in cutaneous squamous cell carcinoma." (PMID 31052530, 2019). "An increased understanding of the alterations of Bcl-2 members and their network of interactions in cancer could be useful to better exploit them as therapeutic targets." (PMID 31825969, 2019). "It is conceivable that targeting regulation of Bcl-2 at the transcriptional level may provide an alternative strategy for cancer therapy." (PMID 31143550, 2019). "However, PdGs exhibit proapoptotic properties in cancer cells by decreasing the expression of the surviving and Bcl-2 genes and triggering Bax and caspases-3 expression, and they also exert minimal toxicity in normal cells." (PMID 31194753, 2019). "Better understanding of Bcl-2 biology may have important clinical significance for better treatment of cancer." (PMID 31143550, 2019).
cancer (continued). "Future studies will be required to determine whether siRNA targeting PRDM10 may serve as novel cancer therapy agents by inhibiting Bcl-2 expression." (PMID 31143550, 2019). "This suggestion is consistent with previous observations indicating that elevated expression of both of these STAT proteins is seen in numerous cancers, where their phosphorylation results in enhanced expression of cell cycle progression (e.g., cyclin D1) and survival (e.g., Bcl-xL and Bcl-2) genes." (PMID 31291965, 2019). "Thus, MBCD inhibited cancer cell viability with concomitant reduction of expressions of BCL2 and Bcl-xL, and enhancement of caspase-3 and Bax transcripts." (PMID 30625181, 2019). "Furthermore, TMPRSS4 promoted cancer cell survival and drug resistance, and both compounds enhanced anoikis sensitivity as well as reduced bcl-2 and survivin levels." (PMID 31292507, 2019). "In HCC cells, Bcl-2 expression is raised that initiates cancer pathogenesis." (PMID 31676815, 2019). "Cancer cells treated with nitidine chloride (NC), matrine, berberine, and subditine showed upregulation of Bax expression and downregulation of Bcl-2 expression." (PMID 31781485, 2019). "In cancer, the antiapoptotic protein Bcl-2 is commonly deregulated and appears to modulate IP3K." (PMID 31097925, 2019). "In this context, B-cell lymphoma 2 (BCL-2) family proteins, notably myeloid cell leukemia-1 (MCL-1), are known for their role in both the development and persistence of AML, and are often associated with cancer-cell survival and resistance to chemotherapy." (PMID 30815228, 2019). "However, we should not forget that therapeutic-regulation of apoptosis particularly by modulating the BCL2 interactome has strong therapeutic potential to combat human disease, including cancer and neurodegenerative disorders." (PMID 31569576, 2019). "In addition, apogossypol-mediated ER membrane reorganisation also prevented BH3 mimetic-mediated apoptosis, which was surprising as apogossypol was originally developed as a pan-BCL-2 inhibitor to induce apoptosis in cancer cells." (PMID 31285422, 2019). "Therefore, the discovery of potent and safe BCL-2 targeting small molecules is necessarily required to impede growth of cancer cells." (PMID 31450709, 2019). "In turn, extracellular lactate is associated with malignant transformation and can regulate cancer-related signaling pathways (e.g., NF-kB/IL-8, HIF1, and PI3K/Akt/mTOR/Bcl-2), angiogenesis, and ATP production, which in turn influence cell proliferation and migration." (PMID 30967136, 2019). "Thus, the development of anti-apoptotic Bcl-2 inhibitors has important implications for cancer treatment and prevention." (PMID 32257914, 2019). "Studies have shown BID and Bcl2 as molecules acting upstream and downstream of MuD, respectively, suggesting that MuD may perform a novel role in the cancer apoptotic pathway." (PMID 31616474, 2019). "For example, one could expect that pro-survival BCL-2 gene levels would largely be up-regulated in cancer types, but it has been demonstrated that such trend cannot be expected to be ubiquitous in cancers." (PMID 31825969, 2019). "Therefore, the high Bax/Bcl-2 ratio appears to be an indicator of good prognostic outcome of cancer." (PMID 31861952, 2019). "This increase might be related to the direct targeting of miR-139 to anti-apoptotic regulator Bcl-2, which is involved in drug resistance and progression of cancer cells." (PMID 31426807, 2019).
cancer (continued). "BNIP3L (Bcl2 and adenovirus E1B 19-kDa-interacting protein 3-like), also known as NIX, are the proteins which interact with Bcl2 and are involved in cell death and autophagy, suggesting that BNIP3L/NIX are implicated in the pathogenesis of cancer." (PMID 30669284, 2019). "The development of specific antagonists of the BCL-2 family has been challenging, mainly due to the high homology of the BH domains and the incomplete understanding of how these proteins interact in specific cancer contexts, but antagonists of the BCL-2 pro-survival pathway have been developed." (PMID 30720718, 2019). "Understanding this mechanism of resistance may also suggest ways to release specific sequestered BH3-proteins from Bcl-XL and Bcl-2 to kill cancer cells more selectively than broadly inhibiting anti-apoptotic proteins." (PMID 30860026, 2019). "Treatment of cancer cells with MBCD showed inhibition of both BCL2 and Bcl-xL transcript levels." (PMID 30625181, 2019). "This renders the anti-apoptotic Bcl-2 proteins important targets in cancer drug design." (PMID 31404252, 2019). "The BCL-2 family of proteins, including anti-apoptotic BCL-2 and pro-apoptotic BAX, are critical regulators of the mitochondrial apoptotic pathway and they have been associated with a more aggressive treatment and drug resistance in cancer chemotherapy." (PMID 30754694, 2019). "Overexpression of Bcl-2 leads to abnormal apoptosis and cancer development." (PMID 31892356, 2019). "BCL2 (B-cell lymphoma-2) is a gene that is overexpressed in many cancers to escape cell death." (PMID 31744202, 2019). "In addition, we also evaluated the protein levels of PARP1, Bax and Bcl‐2, which are typical apoptotic proteins in cancer cells." (PMID 30920152, 2019). "The downregulation of the expression of anti-apoptotic genes such as Bcl-2 and Bcl-X makes cancer cells more vulnerable to apoptosis and, in cellular models with Bcl-2 overexpression, some analogs deactivate the Fas (CD95)-associated protein with death domain, resulting in programmed cell death." (PMID 31013694, 2019). "Here, the authors identify BCL2 genes have differential sensitivities to SF3b-targeting splicing modulators and combination of SF3b-targeting splicing modulators and BCLxL inhibition induces synergistic cytotoxicity in cancer cells." (PMID 30635584, 2019). "Bcl-2 is one of the important apoptotic proteins that play a role in progression of cancer." (PMID 31676815, 2019). "It was reported that Bcl2 can determine the resistance of 5-Fu in carcinoma; hence, we supposed PVT1 may possibly enhance 5-fu resistance in GC via its promotion to Bcl2." (PMID 31205469, 2019). "However, Bcl2 expression decreased after the administration of staurosporine in PaTu 8988t carcinoma cells." (PMID 30686270, 2019). "Furthermore, the expression level of the anti-apoptotic protein Bcl-2, which is overexpressed in many tumors and drives tumorigenesis and chemoresistance, seems to be a determinant for the sensitivity of cancer cells to cisplatin." (PMID 29491433, 2018). "Bcl-2 is a cell survival oncogene that prevents apoptosis, hence promoting cancer malignancies." (PMID 29587429, 2018). "For instance, in almost half of all human cancers, BCL-2 expression is elevated." (PMID 29393886, 2018).